ILK (integrin linked kinase)
Diseases named in the same sentence as ILK in open-access papers (continued):
Sharing a sentence is not in itself a finding about the gene and the disease.
prostate carcinoma (31 papers, 2006 to 2025). A carcinoma that arises from epithelial cells of the prostate gland. "Recently, a dissection of prostate cancer tissue has shown that reactive stroma and inflammation are present at early stages and promote tumor growth by activation of oxidative stress and integrin-linked kinase (ILK) signaling." (PMID 32178267, 2020). "HIF-1α also facilitated the regulatory loop with integrin-linked kinase (ILK) to promote epithelial-mesenchymal transition in breast and prostate cancer cell lines." (PMID 32322559, 2020). "Loss of ILK and talin expression in PC-3 and DU-145 prostate cancer cells respectively resulted in enhanced sensitivity to DZ-50, while talin overexpression suppressed anoikis." (PMID 24497940, 2014). "Loss of expression of the intracellular focal adhesion signaling effectors talin-1 and integrin linked kinase (ILK) sensitized human prostate cancer to anoikis." (PMID 24497940, 2014). "The inhibition of ILK by transfection of dominant-negative ILK results in suppression of cyclin D1 expression and G1/S cell-cycle arrest in prostate cancer cells." (PMID 35778385, 2022). "In contrast, in different datasets lower expression of ILK is observed in bladder, brain, breast, cervical, colorectal, esophageal, head and neck, leukemia, lung, lymphoma, ovarian and prostate cancers." (PMID 35692780, 2022). "Loss-of-function experiments using siRNA or shRNA targeting ILK have demonstrated that knockdown of ILK represses EMT, tumor growth, and metastasis in tongue and prostate cancers through inactivation of the PI3K/AKT pathway." (PMID 35379935, 2022). "We observed that ILK is expressed in invadopodia of invasive breast and prostate cancer cells where it forms protein–protein complexes with NHE1, β1-integrin, NHERF1 and ezrin phosphorylated at T567." (PMID 33671549, 2021). "CP22 was developed as a highly selective inhibitor of ILK and was shown to have antiproliferative effects in both in vitro and in vivo experiments in prostate cancer." (PMID 33256002, 2020). "Inhibition of ILK has been demonstrated to suppress activation of protein kinase Akt, inducing cell cycle arrest and apoptosis in prostate cancer and colon cancer." (PMID 33256002, 2020). "Compound 22 reduces the proliferation of SKOV3 and OV90 cell proliferation: Compound 22 (CP22), is a selective ILK inhibitor that was shown to be antiproliferative in prostate cancer." (PMID 33256002, 2020). "In prostate cancer, the expression of ILK increased significantly with the progression of prostate cancer." (PMID 31897228, 2020). "When comparing CRPC to PC samples, the most significantly altered pathways during progression of prostate cancer include ILK signaling and glucose metabolism-related pathways." (PMID 29563510, 2018). "Similar signalling was also reported in prostate cancers in which ILK increases angiogenesis via the Akt–HIF-1–VEGF pathway." (PMID 25738875, 2015). "ILK is required for centrosome clustering in several breast and prostate cancer cells with supernumary centrosomes." (PMID 24911651, 2014). "Targeting of critical intra- and extracellular focal adhesion components in prostate cancer cells, specifically talin, ILK, integrin-α6 and fibronectin by lead agent DZ-50, lifts anoikis resistance by inhibiting downstream survival signaling by AKT and GSK3β." (PMID 24497940, 2014). "Immunohistochemistry (IHC) revealed a higher ILK expression in primary prostate cancer with respect to the adjacent benign prostate hyperplasia." (PMID 21347395, 2011). "According to this paper, prostate cancer cells secrete VEGF in a ILK-dependent manner via pathways involving Akt→m-TOR (mammalian target of rapamycin)→HIF-1 (hypoxia inducible factor-1)." (PMID 23675014, 2007).
prostate carcinoma (continued). "Not only this one study, but there are tens of thousands such studies like this, such as a recent study first utilized bioinformatics pipeline comprising different techniques to experimentally validate the ILK gene against prostate cancer using shRNA transfection, qPCR, and western blotting." (PMID 40591684, 2025). "Integrin-linked kinase (ILK), plectin (PLEC), paxillin (PXN), talin 1 (TLN1), and vinculin (VCL) are other adhesome proteins that were implicated in prostate cancer and that showed biomarker potential in this cancer type." (PMID 38255186, 2023). "To confirm whether CD82 inhibition of fibronectin-mediated EMT is dependent on fibronectin-receptor signaling events, we overexpressed wild-type FAK and ILK in prostate cancer cells through gene transfection." (PMID 27926483, 2017). "In the present study, using two different androgen-independent human prostate cancer cell lines and DU-145 and PC-3, as in vitro experimental systems, we demonstrated that two distinct intracellular focal adhesion complex components, talin and ILK, are targeted by the lead quinazoline DZ-50." (PMID 24497940, 2014). "Consistently, it has been shown that ILK phosphorylates MYPT1-PP1, leading to its inactivation and promoting tumor progression in breast, colon and prostate cancer cells." (PMID 31926547, 2020). "The activity of ILK kinase was found to be significantly decreased in PARVA-depleted prostate cancer cells, suggesting that the formation of PARVA–ILK complexes is required for the activation of ILK." (PMID 25738875, 2015). "Therefore, targeting HIF-1α expression through ILK inhibition, in combination with androgen deprivation therapy, may be a rational therapeutic strategy to prevent or delay progression to castration-resistant prostate cancer." (PMID 25821081, 2015). "ILK and ERG have been shown to cooperatively drive malignant transformation and epithelial-mesenchymal transition in prostate cancer." (PMID 26230842, 2015). "The anoikis-inducing effect of the lead quanazoline compound DZ-50 was investigated in human prostate cancer cell lines variably expressing the FAC proteins, talin-1 and ILK." (PMID 24497940, 2014). "Inhibition of ILK activity has been shown to disrupt mitotic spindle function (including spindle organization) in HEK 293 cells, HeLa cells, breast and prostate cancer cells." (PMID 24911651, 2014). "Furthermore, ILK regulated both β1-integrin- and NHE1-driven invadopodial ECM proteolysis and cell invasion, thus promoting an invasive phenotype in breast and prostate cancer cells in vitro by coordinating an ECM proteolytic/invasion signal module." (PMID 33671549, 2021). "In prostate cancer, KRAS regulates ILK expression mediated by E2F1 in a KRAS-E2F1-ILK-hnRNP1 loop." (PMID 34233735, 2021). "Centrosome clustering is altered by ILK whether or not the Rb gene product is expressed as this was observed in breast and prostate cancer cells (expressing normal Rb protein levels) and in retinoblastoma lines (devoid of Rb protein expression)." (PMID 24911651, 2014).
cardiac hypertrophy (26 papers, 2008 to 2025). "By binding to the cytoplasmic domain of β-integrins, ILK controls cytoskeletal remodeling and is linked to cardiac contractility, ventricular hypertrophy, and cardiac repair." (PMID 36964489, 2023). "Not only do mutations in ILK contribute to cardiac hypertrophy and contractility, but ILK is a novel cardiotropic factor promoting the transformation of human fetal heart cells to a cardiomyogenic fate as well." (PMID 35089438, 2022). "ILK regulates diverse signal transduction pathways implicated in cardiac hypertrophy and contractility." (PMID 36414707, 2022). "Integrin-linked kinase (ILK) is a widely conserved serine/threonine kinase that regulates diverse signal transduction pathways implicated in cardiac hypertrophy and contractility." (PMID 22666394, 2012). "In light of ILK's role in cardiac pathologies, recent studies have shown that transgenic mice with cardiac-specific over expression of ILK exhibited compensated cardiac hypertrophy whereas ablation of ILK in mice caused more advanced cardiac failure." (PMID 21625516, 2011). "ILK has been both directly and indirectly implicated in cardiac hypertrophy, cardiomyopathy and muscular dystrophy." (PMID 18611274, 2008). "ILK is associated with cardiac contractility, ventricular hypertrophy, and repair." (PMID 32144627, 2021). "Thus, the occurrence of mild cardiac hypertrophy after three weeks of ILK deletion may amplify the initial damage caused by microvascular dysfunction." (PMID 37452166, 2023). "Integrin‐linked kinase (ILK), now known as a mechanoreceptor protein and the physical linker for integrins with the actin cytoskeleton, regulates a variety of signal transduction pathways associated with both cardiac hypertrophy and contractility/force transduction." (PMID 32189431, 2020). "These included pathways related to LXR/RXR activation, cardiac hypertrophy signaling, ILK signaling, production of NO and ROS in macrophages, actin cytoskeleton signaling, fibrosis and cell migration pathways, and acute phase response signaling." (PMID 36928240, 2023). "It was previously shown that ILK elevates the protein translation mediator P70S6 kinase (p70S6K) during cardiac hypertrophy, and independently that p70S6K induces differentiation in human embryonic stem cells." (PMID 22666394, 2012). "For both HCM and healthy hearts, activated pathways in the LA included D-myo-inositol-phosphate biosynthesis, cardiac hypertrophy, actin cytoskeleton, ILK and integrin signaling as well as production of nitric oxide (NO) and reactive oxygen species (ROS) in macrophages." (PMID 36928240, 2023). "It was revealed that ILK adaptively increased in the pressure overloaded cardiac hypertrophy model and could further participate in the activation of CFs." (PMID 36935650, 2022). "Therefore ILK expression alternation was a critical pathophysiological feature that contributes to the transition from adaptive cardiac hypertrophy to cardiac dysfunction." (PMID 21949693, 2011). "Whether impairment of ILK related signaling pathway is the key feature for transition from adaptive cardiac hypertrophy to cardiac dysfunction needs to be clarified." (PMID 21949693, 2011). "Temporally up-regulation of ILK level in non-ischemic myocytes by increased external load is associated with beneficial angiogenesis to maintain infarction-induced cardiac hypertrophy." (PMID 21949693, 2011). "We observed ILK as well as its related pro-angiogenic signaling down-regulated during the transition from adaptive cardiac hypertrophy to cardiac dysfunction; while the sustained ILK expression could maintain responsible angiogenesis in myocardium and improve heart function." (PMID 21949693, 2011). "Cardiac-restricted overexpression of ILK induces cardiac hypertrophy via activation of ERK and p38 MAPK, hence suggesting ILK to be a proximal prohypertrophic signalling activator." (PMID 25485172, 2014).
cardiac hypertrophy (continued). "ILK, which is understood to mediate hypertrophic responses to mechanical stress, is thought to protect the heart by promoting cell survival via activation of AKT, a key regulator of oxidative stress and myocardial hypertrophy." (PMID 32189431, 2020). "In present study, we demonstrated that ILK could induce VEGF expression and a beneficial angiogenesis to maintain cardiac hypertrophy." (PMID 21949693, 2011).
colorectal cancer (26 papers, 2011 to 2025). A primary or metastatic malignant neoplasm that affects the colon or rectum. "For instance, TNS4 facilitates migration, invasion, and epithelial–mesenchymal transition (EMT) in colorectal cancer cells, potentially through upregulation of integrin-linked kinase (ILK), FAK, and Src." (PMID 40906372, 2025). "Interrogation of web-based data-mining platforms, showed upregulation of ILK expression in tumors and adjacent-non tumor tissue of colorectal cancer (CRC) associated with poor survival and advanced stages." (PMID 35692780, 2022). "In the context of colorectal cancer, we notably brought to light a PrPC-dependent activation of the integrin linked kinase (ILK) that relays its control on cell proliferation." (PMID 34638517, 2021). "Other cancer progression pathways that were activated included colorectal cancer metastasis signaling and ILK signaling, which is implicated in connecting integrins to the cytoskeleton." (PMID 33347497, 2020). "Overexpressed thymosin β4 (Tβ4) induces EMT in colorectal carcinoma by increasing integrin-linked kinase (ILK) complex formation with particularly interesting new cysteine-histidine rich protein (PINCH)." (PMID 21362178, 2011). "Currently, it has been documented that ILK is associated with colorectal cancer." (PMID 35481240, 2022). "Previously, it has been suggested that integrin-linked kinase (ILK) may work as a downstream target of Tensin4 to mediate its oncogenic function in colorectal cancer." (PMID 26035355, 2015). "Recent work also suggests that ILK is involved in the development of immune tolerance in CMS4, a mesenchymal subtype of colorectal cancer associated with poor prognosis and chemoresistance." (PMID 35804980, 2022). "NF-κB and IL-6 and other inflammatory cytokines are also induced by ILK in experimental colitis and colorectal cancer." (PMID 34163519, 2021). "In colorectal cancer cells, overexpression of ILK promoted proliferation, metastasis, and invasion ability." (PMID 31897228, 2020). "The identified pathways included GP6 signaling, IL-8 signaling, ILK signaling, neuroinflammation signaling pathway, colorectal cancer metastasis signaling, leukocyte extravasation signaling, and osteoarthritis pathway." (PMID 32315343, 2020). "A study found that ILK is up-regulated in colorectal cancer and other tumors." (PMID 35429970, 2022). "Similarly, in vitro ILK upregulation in SW480 colorectal cancer cells promotes upregulation of Snail, slug, vimentin and MMP9, subsequently increasing proliferative, migratory and invasive activities." (PMID 34163519, 2021). "For instance, the expression of ILK in human tissues from primary colorectal carcinomas and lymph node metastases examined by immunohistochemistry (IHC) reveal expression levels as very low, high and significantly higher in normal tissue, primary tumor and lymph node metastases, respectively." (PMID 34163519, 2021). "In colorectal carcinoma it was demonstrated that Tβ4 triggers EMT transition by ILK upregulation." (PMID 31921836, 2019). "Also, knockdown of ILK has been shown to reduce levels of parvins in intestinal epithelial cells and expression of α- and β-parvin in human colorectal cancer positively correlated with levels of ILK." (PMID 29755929, 2018). "Tβ4 also triggers an EMT in colorectal carcinoma by upregulating ILK." (PMID 26006229, 2015). "According to reports, ILK is overexpressed in colorectal cancer, bladder cancer, and many other tumor tissue types and is associated with TNM (‘tumor,’ ‘nodes,’ and ‘metastasis’) stage, lymph node metastasis, and differentiation, thus indicating ILK as a potential anti-cancer therapeutic target." (PMID 35587162, 2022). "In addition, the activation of ILK by TB4 induced EMT in colorectal cancer cells." (PMID 28630423, 2017). "To establish a correlation between chronic intestinal inflammation and colorectal cancer (CRC), we investigated the role of myeloid-ILK in mouse models of CRC." (PMID 38077324, 2023).
colorectal cancer (continued). "Overexpression of ILK in colorectal cancer cells results in activation of NF-kB and promotion of EMT, while depletion of ILK expression or inhibition of NF-kB suppresses EMT in these cells, indicating a role of ILK-mediated NF-kB signaling in colon cancer." (PMID 35804980, 2022). "In colorectal cancer (CRC), increased ILK expression in patients correlates with markers of EMT and CSCs and is associated with metastasis and chemoresistance." (PMID 35804980, 2022). "CDKN2A, CMTM8, ILK, and their co-expression genes were enriched in the following pathways: ILK pathway, TGF-β pathway, epithelial to mesenchymal transition in colorectal cancer, integrin-mediated cell adhesion, signaling by Notch, and so on." (PMID 35429970, 2022). "This is in accord with IHC examination of human colorectal carcinoma tissues, which showed that the expression of EMT-related proteins was positively correlated with ILK expression." (PMID 34163519, 2021). "Inhibition of ILK/AKT decreases miR-21 in vestibular schwannoma and meningioma cells, and targeting miR-21 with antisense oligonucleotides (ASOs) inhibits growth and metastasis via upregulation of DUSP8 in colorectal carcinoma." (PMID 32260415, 2020). "The contribution of ILK to cancer-induced MMT has never been described before, although its involvement was reported as being critical for EMT in colorectal cancer, adenomyosis, and glomerulonephritis." (PMID 31086083, 2019).